EIF3D (eukaryotic translation initiation factor 3 subunit D)
Diseases named in the same sentence as EIF3D in open-access papers (continued):
Sharing a sentence is not in itself a finding about the gene and the disease.
tumor (29 papers, 2014 to 2025). "As being discovered in our study, all these high levels of eIF3D are associated with advanced tumour stage, indicating its potential role in tumour development." (PMID 31885740, 2019). "High eIF3d levels were associated with advanced tumor stage and metastasis and were correlated with poor prognosis in 92 patients with GBC." (PMID 28594409, 2017). "We found that downregulation of EIF3D suppressed Ki67 staining levels in tumor tissues, suggesting the inhibition of tumor cell proliferation." (PMID 35104170, 2022). "Subsequently, we conducted immunoblot assays and found the high EIF3D expression in three representative tumor tissues compared with the corresponding normal tissues." (PMID 35104170, 2022). "eIF3C, eIF3D and eIF4E even correlated with tumor grade as their expression was significantly higher in HGG than in LGG." (PMID 33807050, 2021). "In prostate cancer, levels of apoptosis in tumour cells with high eIF3d expression are reduced, with increased invasive ability and a poor prognosis." (PMID 31118081, 2019). "Previous studies on eIF3d in tumours have shown that over expression leads to the abnormal proliferation of tumour cells." (PMID 31118081, 2019). "Previous reports have indicated that eIF3d can serve as a marker for tumour metastasis and prognosis." (PMID 31118081, 2019). "Previous studies have reported that eIF3d regulates tumour cell function via different signalling pathways." (PMID 31118081, 2019). "The high eIF3D expression group had a significantly larger ratio of patients with residual tumour (13/4 vs. 163/176, p = 0.0257) and targeted molecular therapy (85/65 vs. 138/164, p = 0.0357)." (PMID 31885740, 2019). "The immunostaining intensity of eIF3d correlates positively with the tumor clinical stage and metastasis, and elevated expression of eIF3d significantly correlated with poor survival in GBC patients." (PMID 28594409, 2017). "To explore the biological connection of GRK2 with the tumor-promoting function of eIF3d, we examined the effect of GRK2 re-expression in eIF3d knockdown stable NOZ cells on tumorigenicity." (PMID 28594409, 2017). "Tumor nodules in the liver and lung carried higher incidence in those mice inoculated with scramble cells compared with those mice injected with the eIF3d knockdown cells, as revealed by gross examination and H&E staining." (PMID 28594409, 2017). "We found that eIF3d knockdown significantly inhibited xenograft tumor formation and growth in nude mice." (PMID 28594409, 2017). "We evaluated the knockdown efficiency of eIF3d in transplanted tumor tissues from the mice by immunoblotting and IHC staining." (PMID 28594409, 2017). "Moreover, CRABP2 and Eukaryotic Translation Initiation Factor 3 Subunit D (EIF3D) were found to promote tumor growth by activating FAK through the Integrin β1/FAK/ERK and GRP78-related pathways, respectively." (PMID 41148856, 2025). "Nevertheless, it remains to be elucidated whether EIF3D regulates AS in a manner that mediates disparities in the tumour microenvironment." (PMID 38535990, 2024). "Collectively, these findings suggest that EIF3D-mediated expression levels of immune-related genes and immune cell apoptosis may also be correlated with tumor responsiveness to immunotherapy." (PMID 38535990, 2024). "The results showed that tumor growth in the EIF3D shRNA group was slower than that of the control." (PMID 35104170, 2022). "The staining of BRCA1, ABI1, and EIF3D was medium in tumor tissue but low in normal tissue." (PMID 36233273, 2022). "Presently, eIF3d is being used for gene therapy in tumours, and increasing eIF3d expression in HIV-infected patients, thereby delaying disease progression, may provide innovative ideas for immune intervention." (PMID 31118081, 2019).
tumor (continued). "Chi-square analysis revealed that the highly expressed eIF3D group had larger ratios of patients with advanced pathological stage (68/40 vs. 184/206, p = 0.0046), residual tumour (13/4 vs. 163/176, p = 0.0257), and targeted molecular therapy (85/65 vs. 138/164, p = 0.0357)." (PMID 31885740, 2019). "Levels of nine eIF3 subunits involving eIF3A, eIF3B, eIF3C, eIF3D, eIF3E, eIF3H, eIF3I, eIF3J, and eIF3M were significantly increased in cancer tissues, whereas the eIF3L expression level in tumours was independently decreased than that of normal tissues (p < 0.05)." (PMID 31885740, 2019). "Recent studies have examined the relationship between EIF3D and tumours." (PMID 28203520, 2016). "Furthermore, tumour differentiation indicated that EIF3D expression gradually increased from G1 to G3 (P = 0.0305)." (PMID 28203520, 2016). "To elucidate the possible impact of EIF3D on BC, we further investigated the impact of its knockdown onto the malignant phenotype of T24M cells, including impact on cell proliferation, migration and colony forming ability in vitro and tumor growth in NOD/SCID T24M xenografts." (PMID 29050215, 2017). "IHC staining with specific antibody against PCNA indicated in the eIF3d depletion tumor sections that there were fewer proliferative cells, however, increased staining intensity for cleaved caspase-3 was observed, indicating significantly increased apoptosis cells in eIF3d shRNA xenograft tumors." (PMID 28594409, 2017). "In addition to its tumorigenic roles, this study also showed that eIF3d enhances tumor metastasis in vitro and in vivo, indicating that overexpression of eIF3d may result in metastasis-related genetic alteration in GBC cell lines." (PMID 28594409, 2017). "Through pseudo-time analysis, we identified genes such as NCBP2, EIF3D, and NUDT4 boost the occurrence and development of malignant tumor epithelial cells, providing guidance for identifying potential therapeutic targets for CRC." (PMID 41406096, 2025). "For instance, EIF3D stabilizes GRK2 protein by blocking ubiquitin-mediated degradation, activating PI3K/Akt signaling, and promoting tumor cell proliferation and migration." (PMID 40018039, 2025). "In future studies, we plan to investigate the synergistic effect of LARP1 with other known prognostic molecules (such as EIF3D, EIF1, METTL1) in HNSCC, particularly their potential interactions in tumor cell growth, metastasis, and immune evasion." (PMID 40018039, 2025). "EIF3D is elevated in gallbladder cancer (GBC) and promotes the proliferation and migration of malignant tumor cells." (PMID 36226166, 2022). "Difference is found in the expression of EIF3A, EIF3B, EIF3D, EIF3F, EIF3H, EIF3J, and EIF3M in different tumor stages." (PMID 36051357, 2022). "As for eIF3D DNA methylation in LUAD, the methylation status of 23 CpG sites was measured by Methylation 450k, and among which nine were hypomethylated in tumour tissues (n = 455) compared with the adjacent counterparts (n = 31)." (PMID 31885740, 2019). "Additionally, quantitative immunohistochemical analysis revealed that the expression of EIF3D, EIF1, LARP1, and METTL1 in the tumor group was significantly higher than in adjacent tissues." (PMID 40018039, 2025). "Most tumor cells expressed NCBP2, EIF3D, and NUDT4 suggesting that m7G-related genes may play a significant role in tumor development." (PMID 41406096, 2025). "In addition, downregulation of EIF3D also decreased the expression of EIF3D, CD133, GRP78, and phosphorylated FAK, in tumor tissues, further confirming the previous findings." (PMID 35104170, 2022). "Similarly, in LUSC, higher expression of AGO2, EIF3D, and LSM1 were positively correlated with tumor stem cell score but negatively correlated with immune infiltration degrees, indicating a poor prognosis." (PMID 36226166, 2022). "In addition, EIF3d, UBR5, BRD4, TRIM31 and LINC00152 are demonstrated to contribute to cell growth or tumor metastasis of GBC cells via PI3K/AKT pathway." (PMID 32333246, 2020).
tumor (continued). "Our study demonstrated that a reduction in eIF3d expression in human CD8+ T cells attenuated cell proliferation and secretion of IFN-γ and promoted apoptosis, which was consistent with the finding of the function of this protein in tumour cells." (PMID 31118081, 2019). "Except EIF3E and EIF3F found down-regulated and conferred tumor suppressive activity in cancers, majority of EIF3 members including EIF3A, EIF3B, EIF3C, EIF3D, EIF3H, EIF3I and EIF3M were up-regulated and played important roles in tumor progression of multiple cancer types." (PMID 29568350, 2018). "EIF3d promotes GBC cell proliferation, migration and tumor growth in vitro and in vivo." (PMID 28594409, 2017). "The expression level of eIF3d was significantly higher in tumor tissues than that in their non-tumor counterparts." (PMID 28594409, 2017). "In our study, EIF3D subunit was found to be up-regulated in MIBC compared to NMIBC and the knockdown of this factor resulted in the reduction of T24M cell proliferation, migration and colony forming ability in vitro, and decreased tumor growth in a xenograft mouse model in vivo." (PMID 29050215, 2017). "Besides, nine eIF3 subunits beyond eIF3D were found aberrantly expressed in LUAD tissues and in which the expression levels of five subunits (eIF3B, eIF3C, eIF3E, eIF3H, and eIF3J) increased in LUAD patients with high tumour stage, implicating their roles in the maintenance or progression of LUAD." (PMID 31885740, 2019). "Furthermore, restoration of GRK2 expression level significantly rescued the hyperproliferative phenotype, colony formation and migration capacities of the eIF3d knockdown NOZ cells, although it does not fully restored tumor malignancy as compared with the control group." (PMID 28594409, 2017).
cancer (25 papers, 2016 to 2025). A tumor composed of atypical neoplastic, often pleomorphic cells that invade other tissues. "Three subunits of the eukaryotic initiation factor 3 (eIF3) complex are correlated with cancer development—subunit eIF3d possesses cap-binding activity; eIF3G is associated with cancer progression; eIF3h interacts with METTL3." (PMID 33808751, 2021). "Although it is unknown if the discrepancy between these studies is due to different cancer types, the fact that eIF3d associates with prognosis, better or worse, suggests that it may play a role in therapeutic response or in disease aggressiveness or progression." (PMID 36997088, 2023). "In certain types of cancers, the eIF3d and eIF4G2 driven mechanism is also used to bypass the global sequestration of eIF4E, thereby allowing EMT, which is a crucial indicator for cancer progression to occur." (PMID 39971159, 2025). "This study lays the foundation for a quantitative understanding of eIF3d driven translation to guide in the design and development of novel therapeutic targets in cancer research." (PMID 39971159, 2025). "This process is further modulated by eIF3d-mediated translational recovery, which enhances proteotoxicity selectively in cancer cells undergoing paraptosis upon VCP inhibition." (PMID 38218922, 2024). "eIF3D activation ensured a latent phenotype in cancer cells with migratory features via eIF3D-dependent synthesis of proteins involved in cell motility." (PMID 38418814, 2024). "Investigations of human cancer tissue consistently exhibited that EIF3D increased expression with an unfavorable prognosis in gastric, gallbladder, lung, and liver cancers." (PMID 38535990, 2024). "EIF3D is a subfamily member of the eukaryotic translation initiation factor 3 (eIF3), has been observed in various human cancers, implicating its involvement in tumorigenesis." (PMID 38305770, 2024). "This study provides the first evidence that EIF3D can function as an RNA splicing regulator, orchestrating IGAS and promoting pro-cancer effects in HNSC by associating with immune-related transcripts." (PMID 38535990, 2024). "Collectively, these results underscore the role of EIF3D in promoting FaDu cell proliferation, migration, and invasion while inhibiting apoptosis, providing further evidence that EIF3D plays a pro-cancer role in the progression of HNSC." (PMID 38535990, 2024). "Future systematic investigations including rescue studies are expected to elucidate the mechanism of eIF3d action and the missing link between eIF3d and other cellular signaling pathways in different types of human cancers." (PMID 36997088, 2023). "Recent studies concluded that the EIF3D expression is critical to the occurrence of cancer by promoting protein synthesis." (PMID 35602299, 2022). "EIF3D was identified to enhance the sensitivity of cancer cells to some chemotherapeutics, such as hydroxyurea, chelerythrine, and vorinostat, while LARP1 weakened the sensitivity of denileukin diftitox ontak." (PMID 35602299, 2022). "Previous studies demonstrated that eIF3D affected cancer cell growth via multiple signaling pathways." (PMID 31885740, 2019). "Other mRNAs such as BARX1, EIF3D, PPP1R7, and HSD17B1 are also known to be associated with different cancers or other diseases." (PMID 29270229, 2017). "Upregulation of eIF3a, eIF3b, eIF3c, eIF3d, eIF3e, eIF3h, and eIF3i along with reduced levels of eIF3e and eIF3f has been observed in several cancers." (PMID 28083147, 2016). "eIF3d is also overexpressed in many types of cancers such as cervical, ovarian, lung, and renal cell carcinomas, and may serve as a potential novel biomarker of disease progression." (PMID 39971159, 2025). "For this purpose, the eIF3d protein is chosenas a potential biomarker for cancer diagnosis." (PMID 40114326, 2025).
cancer (continued). "We suggest a model that could apply to many other situations, and indeed beyond stem cell biology, to cancer, where translation, and increasingly eIF3d, have been shown to sustain cell proliferation and survival." (PMID 40067813, 2025). "Furthermore, we emphasize the critical role of eukaryotic translation initiation factor 3 subunit D (eIF3d) as a mediator for translational recovery in cancer cells exposed to proteotoxic stress." (PMID 38218922, 2024). "Multiple studies also illustrated EIF3D’s pivotal role in carcinogenesis through the regulation of translational initiation and oncogene expression, suggesting the potential utility as both a novel biomarker and a target for cancer therapeutics." (PMID 38535990, 2024). "Although the cause for the discrepancy in these studies is unknown, these findings suggest that eIF3d may regulate cell proliferation by regulating cell cycle progression but in a cell line or cancer type–dependent manner." (PMID 36997088, 2023). "The involvement of eIF3d in cell cycle regulation has been reported in different cancer cell types." (PMID 36997088, 2023). "Based on our results, the overexpression of downstream proteins in protein synthesis-related pathways, such as EIF3D, may be contributing to the acquired resistance of cancer cells to mTOR inhibition, a hypothesis meriting further investigation." (PMID 29050215, 2017). "Furthermore, a decreased migratory capacity of the cancer cells upon suppression of EIF3D was also described." (PMID 29050215, 2017). "Recent evidence suggests that dysregulated eIF3d expression may be critical in various genetic disorders as well as cancer." (PMID 28594409, 2017). "The increasing number of studies indicates that increased level of EIF3D in cancer may be a common feature in several malignancies." (PMID 29050215, 2017). "Essentially, this data suggests that the novel function of eIF3d-eIF3e in maintaining mitochondrial respiration components and serving to adjust metabolic pathways may help us better understand how the cancer-promoting properties of the eIF3 complex emerge." (PMID 28083147, 2016). "A number of additional studies have also shown that eIF3d is involved in tumorigenesis via translational regulation of oncogene expression, suggesting that it may serve potentially as a novel biomarker and cancer therapeutic target." (PMID 36997088, 2023). "Furthermore, a recent study suggests the role of eIF3d-eIF3e module within the eIF3 complex that regulates the translation of specific mRNAs involved in maintaining metabolic pathways that are likely disrupted in cancer cells." (PMID 28083147, 2016). "Among these cancer relapse-relevant genes, METTL16, FTO, EIF3D, and EIF3I were good prognostic factors, while TRA2A, HNRNPA2B1, and YTHDC2 were bad ones." (PMID 33273988, 2020). "By exploring the modifications of effector proteins in signaling pathways responsible for cell growth and apoptosis, the activations of three cancer-related molecules—AKT, HSP27, and SAPK/JNK—were found to be reduced by eIF3D knockdown in NSCLC cells." (PMID 31885740, 2019). "eIF3d knockdown in NSCLC cells resulted in decreased phosphorylation and thus inhibition of AKT, HSP27, and SAPK/JNK (involved in cellular growth and cancer progression pathways)." (PMID 28083147, 2016). "Depletion of eIF3d affected multiple components of the MAPK signaling pathways, which plays a critical role in the regulation of cell proliferation and cancer development and progression." (PMID 39495207, 2024). "Additionally, eIF3d critically contributed to translational recovery, leading to ATF4 upregulation and enhancing cancer cells’ sensitivity." (PMID 38218922, 2024). "Additionally, analysis of drug sensitivity indicated that EIF3D, EIF4A1, and LARP1 expressed by cancer cells greatly influenced the sensitivity of the cells to chemotherapy." (PMID 35602299, 2022).
cancer (continued). "The translation initiation factor subunit EIF3D and the splicing factor HNRNPA2B1 can be independent prognostic factors which may contribute to retardation and promotion of cancer progression, respectively, through affecting cancer-related processes such as cell cycle." (PMID 33273988, 2020). "Being consistent with our findings, the strong correlations between high eIF3D expression and poor OS outcomes were also observed in patients with GC and GBC, supporting its high potential role to serve as a useful prognostic marker and therapeutic target for the treatment of these cancers." (PMID 31885740, 2019). "Although the mechanism of eIF3d involvement in cancer cell proliferation has not been elucidated, there is evidence that eIF3d may be involved in several signaling pathways that could affect cancer-related processes." (PMID 36997088, 2023). "However, more regulator genes negatively related to those compounds, like AGO2, DCP2, EIF3D, EIF4E, LARP1, and NCBP3 (related to 30 cancer drugs both in GDSC and CTRP), indicating the patients with higher mRNA expression level of these regulator genes might sensitive to these compounds." (PMID 36092891, 2022). "The eIF3D-dependent translation also enabled the synthesis of insulin receptors (INSR) and insulin-like growth factor 1 receptors (IGF1R), and the synthesis of proteins involved in the JAK/STAT pathway in non-dividing cancer cells." (PMID 38418814, 2024). "In addition, proteins that have been related to other cancers but not to BC yet, were also identified, such as fibulin-2 (FBLN2), tissue alpha-L-fucosidase (FUCA1), staphylococcal nuclease domain-containing protein 1 (SND1), and EIF3D." (PMID 29050215, 2017).